CAMK2D (calcium/calmodulin dependent protein kinase II delta)
Diseases named in the same sentence as CAMK2D in open-access papers (continued):
Sharing a sentence is not in itself a finding about the gene and the disease.
conduction disorders (1 paper, 2021). "Similar to our differential gene expression analysis, we focused on alternative splicing events affecting genes involved in regulation of cardiac ion transport and previously implicated in conduction disorders — Scn5a, Kcnd3, Kcnip2, Ryr2, and Camk2d." (PMID 33497365, 2021).
depression (1 paper, 2023). "The overlapping genes in these activation pathways were Camk2a and calcium/calmodulin-dependent protein kinase II delta (Camk2d), which have been linked to the development of depression." (PMID 37505566, 2023). "We computed the up-regulation network using the Cytohubba plugin in Cytoscape and found that both Camk2a and Camk2d were on major nodes of the up-regulated ceRNA network mRNA, suggesting that Camk2a and Camk2d play an active role in depression." (PMID 37505566, 2023).
Hypertension (1 paper, 2024). The presence of chronic increased pressure in the systemic arterial system. "The results revealed a cluster of proteins, including the SRC family, CAMK2B, CAMK2D, TEC, GSK3, VAV, and RAC, which were markedly upregulated in patients with hypertension compared to those with prehypertension (fold change ≥ 1.6 or ≤−1.6, area under the curve ≥ 0.8, and q-value < 0.05)." (PMID 38732116, 2024).
ischemic stroke (1 paper, 2024). A stroke disorder caused by obstruction of blood flow to the brain, due to thrombotic (local blood clot formation) or embolic (due to a blood clot or other material traveling from another site) event. "The expression of CaMKIIδ is increased by ischemic stroke primary neurons dependent on two CAMK2D-associated lncRNAs (C2dat1 and C2dat2)." (PMID 39021183, 2024).
lymphoma (1 paper, 2025). A malignant (clonal) proliferation of B- lymphocytes or T- lymphocytes which involves the lymph nodes, bone marrow and/or extranodal sites. "Knockout CAMK2D in B‐cell lineage also suppressed DEL lymphoma growth: we observed delayed onset of lymphoma and death, reduced lymph node enlargement, and splenomegaly." (PMID 39840457, 2025). "In summary, lipid profile analysis indicated that CAMK2D knockout decreased FAO and lipolysis, which led to lipid accumulation in lymphoma cells." (PMID 39840457, 2025).
nicotine addiction (1 paper, 2021). "CAMK2D is part of a larger family of CAMKII, a key component in the common five pathways involved in alcohol, cocaine, opioids, and nicotine addiction." (PMID 33540941, 2021).
omphalocele (1 paper, 2018). Omphalocele is an embryopathy classified in the group of abdominal celosomias and is characterized by a large hernia of the abdominal wall, centered on the umbilical cord, in which the protruding viscera are protected by a sac. "In our study, downregulation of WNT11, PRKCA and CaMK2D genes after TiO2 NPs treatment (10 μg/ml) possibly interfered with actin-cytoskeleton organization, cell movement and cell adhesion, thus disrupting noncanonical Wnt/Ca2+ signaling that resulted in omphalocele." (PMID 29555972, 2018).
schizophrenia (1 paper, 2020). A major psychotic disorder characterized by abnormalities in the perception or expression of reality. "This trend was consistent with our results that CAMK2D expression was significantly lower in schizophrenia patients." (PMID 32565801, 2020).
Stroke (1 paper, 2018). Sudden impairment of blood flow to a part of the brain due to occlusion or rupture of an artery to the brain. "We further aimed to assess the potential role of CKB, CaMK2B, CaMK2D, CaMK2A and CMPK as biomarkers of stroke." (PMID 29784938, 2018). "Notably, CaMK2B, but not CaMK2A neither CaMK2D, appeared as a valuable indicator of stroke patient functional outcome." (PMID 29784938, 2018).
vascular dementia (1 paper, 2025). A degenerative vascular disorder affecting the brain. "Loci CAMK2D and ATPase phospholipid transporting 8A2 (ATP8A2) were also replicated with these two exposures for vascular dementia, whereas loci iodothyronine deiodinase 2 (DIO2) and PSMG1 were replicated with oily fish intake and ω-3 concentrations." (PMID 40949174, 2025).
cancer (11 papers, 2015 to 2026). A tumor composed of atypical neoplastic, often pleomorphic cells that invade other tissues. "Previous studies have shown that overexpression of CAMK2D inhibits proliferation, migration and invasion in cancer cells." (PMID 34131397, 2021). "CAMK2B is expressed in neural tissues and CAMK2D in heart and skeletal muscles with little information on cancers." (PMID 32483123, 2020). "This suggests that CAMK2D may negatively affect cancer formation mechanisms by becoming less expressed." (PMID 40579643, 2025). "CAMK2D regulates differentiation, proliferation, and apoptosis in cancer cells." (PMID 38361124, 2024). "In addition to altering major metabolic pathways, our gene set enrichment analysis showed that other cancer‐related pathways, including the general apoptosis pathway and inflammation pathways such as INFα response, TNFα response, and INFγ response, are affected after CAMK2D knockout." (PMID 39840457, 2025). "AKT1 is involved in cell proliferation and survival, while CAMK2D, a member of the CAMK family, activates cancer cell proliferarion." (PMID 27821810, 2016). "In our study, five DEPs (CD44, Stat3, CAMK2D, CAMK2B and CAMK2G) were identified in the proteoglycans in cancer signaling pathway, which worked together to modulate functions of this pathway, such as cell migration and invasion, cell adhesion, cell growth and survival." (PMID 36678534, 2022). "In addition, we identify CAMK2D and CAMK2G as downstream effectors of PEAK1 in TNBC and ‘repurposing’ of the second generation CAMK2 inhibitor RA306 as a potential therapeutic strategy against oncogenic PEAK1 signalling in poor prognosis human cancers such as TNBC." (PMID 39984440, 2025).
tumor (6 papers, 2020 to 2025). "We found that CAMK2D/BAP1-DKO reduced cell proliferation, strongly suggesting that CAMK2D might play a critical role in the tumor growth of BAP1-deficient MMe cells." (PMID 37479714, 2023). "Moreover, BAP1-KO had a negligible effect on cell proliferation, whereas CAMK2D/BAP1-DKO reduced cell proliferation, suggesting that an emerging BAP1-CAMK2D axis might play a critical role in the tumor growth of BAP1-deficient MMe cells." (PMID 37479714, 2023). "Gross anatomy revealed reduced tumor infiltration in lymphoid organs, with smaller lymph nodes, and spleen in EμMYC: Camk2d‐/‐ mice." (PMID 39840457, 2025). "Among these genes, CAMK2D was considered to be a tumor suppressor, involved in the proliferation and migration of tumor cells." (PMID 34131397, 2021). "Our study showed that CAMK2D acted as a tumor suppressor that interfered with miR-135b-induced GC cells migration and invasion." (PMID 34131397, 2021). "Further in vitro and in vivo functional assays validated that miR-135b promoted GC progression and metastasis through directly targeting CAMK2D, a newly discovered tumor suppressor gene." (PMID 34131397, 2021). "Third, the direct binding site between miR-135b and CAMK2D was confirmed by luciferase reporter analysis, and the miR-135b-induced tumor progression was partially antagonized by CAMK2D ectopic expression." (PMID 34131397, 2021). "As expected, CAMK2D deletion in all these cells significantly inhibited tumor cell proliferation." (PMID 39840457, 2025). "Hub gene Camk2d was the most significantly changed gene within a downregulated module (i.e., muscle contraction) and Vsnl1 gene, related to cell cycle checkpoints, is highly expressed in the invasive tumor group." (PMID 35158756, 2022). "CAMK2D was found to be the direct target of miR-135b, serving as a tumor suppressor in GC cells." (PMID 34131397, 2021). "Additionally, the protein level of CAMK2D was mainly decreased in tumor tissues, as well as confirmed by immunohistochemistry (IHC) staining." (PMID 34131397, 2021). "In addition, CAMK2D appeared to be regulated by miRNA-30, known as a tumor suppressor miRNA." (PMID 33540941, 2021). "We further detected the expression level of CAMK2D and EMT-related proteins in tumor tissues derived from xenografts models." (PMID 34131397, 2021). "CAMK2D has also been found to be a downstream effector of interferon-γ (IFN-γ), indicating that CAMK2D may be involved in the regulation of tumor immune microenvironment." (PMID 34131397, 2021). "Interestingly, CAMK2D can be targeted by miR-146a and is consistently shown to suppress the expression of matrix-related genes, indicated that CAMK2D may also be involved in the EMT process in tumor cells." (PMID 34131397, 2021).
cardiac disease (3 papers, 2016 to 2025). "CAMK2D is linked to heart disease, and MAPK9/10 are involved in inflammation, apoptosis, and proliferation." (PMID 41257548, 2025). "CAMK2D contributes to myocardial damage by influencing the expression of inflammatory gene, serves as an inducer of cardiac disease." (PMID 39014511, 2024). "Recent experimentally validated targets for miR-185, such as Camk2d, Ncx1, and Nfatc3 have been related to cardiac diseases." (PMID 27137793, 2016).
CAMK2D also shares sentences with these, for which no sentence is quoted: diabetes (4 papers); prostate carcinoma (2); Anxiety (1); atherosclerosis (1); atrial fibrillation (1); autism spectrum disorder (1); B Cell Lymphoma (1); cardiovascular diseases (1); Cyanosis (1); dementia (1); diffuse large B-cell lymphoma (1); esophageal cancer (1); fibrosis (1); liver cancer (1); malignant glioma (1); malignant mesothelioma (1); metabolic syndrome (1); metastatic prostate carcinoma (1); myotonic dystrophy type 1 (1); osteoarthritis (1); pancreatic cancer (1); Parkinson disease (1); sarcoidosis (1); sleep-disordered breathing (1); Tetralogy of Fallot (1); tumor predisposition syndrome (1); ulcerative colitis (1); uterine cancer (1); Ventricular arrhythmia (1); Ventricular hypertrophy (1).
A further 1 disease shares a sentence with CAMK2D in 1 paper.